PKP4 (plakophilin 4)
Description:
Plays a role as a regulator of Rho activity during cytokinesis. May play a role in junctional plaques.
Synonyms: p0071
Tractability: Antibody: UniProt places it where antibodies can reach, with high confidence; its Gene Ontology location is reachable by antibodies, with high confidence. PROTAC: ubiquitination databases record sites on it; its protein half-life has been measured.
Gene: Protein-coding gene on chromosome 2 (158,456,900 to 158,682,879, forward strand). Ensembl gene ENSG00000144283.
Subcellular location: Cell junction, desmosome; Cytoplasm, cytoskeleton, spindle; Midbody; Cell membrane
Subcellular location (Human Protein Atlas): Cell Junctions; Plasma membrane
Pathways (Reactome):
Signal Transduction: RND1 GTPase cycle; RND2 GTPase cycle; RND3 GTPase cycle
Developmental Biology: Formation of the cornified envelope; Keratinization
Gene Ontology:
Molecular function: protein binding; cadherin binding
Biological process: positive regulation of cytokinesis; regulation of Rho protein signal transduction; cell-cell adhesion; cell-cell junction assembly; cell-cell signaling; regulation of cell adhesion
Cellular component: cell junction; cell-cell contact zone; cell-cell junction; cytoplasm; cytoplasmic side of plasma membrane; cytoskeleton; desmosome; midbody; mitotic spindle; perinuclear region of cytoplasm; plasma membrane; spindle midzone; spindle pole; adherens junction; cornified envelope; nucleus; organelle; postsynaptic density; spindle
Genetic constraint (gnomAD): Loss-of-function variants: 69 observed, 112.18 expected, observed/expected ratio (o/e) 0.62, 90% interval 0.51 to 0.75. The upper end of that interval is the gene's LOEUF score, 0.75, which puts it in group 3 of 6, group 1 being the genes least tolerant of losing a copy. Missense variants: 1,159 observed, 1,321.3 expected, observed/expected ratio (o/e) 0.88, 90% interval 0.83 to 0.92. Synonymous variants: 494 observed, 524.01 expected, observed/expected ratio (o/e) 0.94, 90% interval 0.88 to 1.02.
Homologues: Orthologues: chimpanzee PKP4 (99% identical), macaque PKP4 (99% identical), dog PKP4 (98% identical), rabbit PKP4 (98% identical), guinea pig PKP4 (97% identical), mouse Pkp4 (96% identical), rat Pkp4 (93% identical), pig PKP4 (92% identical), tropical clawed frog pkp4 (82% identical), zebrafish pkp4 (62% identical). Paralogues in human: CTNND2 (51% identical), ARVCF (29% identical), CTNND1 (27% identical), PKP2 (19% identical), PKP3 (18% identical), PKP1 (18% identical).
Diseases named in the same sentence as PKP4 in open-access papers:
PKP4 is named in the same sentence as 33 diseases in open-access papers, as found by Europe PMC text mining. Sharing a sentence is not in itself a finding about the gene and the disease. The quoted sentences say what the papers report.
breast cancer (3 papers, 2015 to 2021). A primary or metastatic malignant neoplasm involving the breast. "Potential oncogenes amplified in the breast cancer include GREB1, NRXN1, MGAT5, PKP4, DAPL1, ITGB6, and RBMS1, which may be implicated in carcinogenesis, proliferation, and invasion." (PMID 26432421, 2015).
cardiomyopathy (2 papers, 2016 to 2018). A disease of the heart muscle or myocardium proper. "Upregulated genes linked to cardiomyopathy included Pkp2, Dst, Dsg2 and Jup; downregulated genes included Pkp1, Dsg1a, Pkp4, Vcl, Gja1 and Ctnna1." (PMID 26935106, 2016).
arrhythmogenic right ventricular cardiomyopathy (1 paper, 2016). "Digenic heterozygosity of mutations in desmosomal genes such as PKP4 gene has been found to play a role in the variable phenotype in arrhythmogenic right ventricular cardiomyopathy." (PMID 27182706, 2016).
autism (1 paper, 2019). Persistent deficits in social interaction and communication and interaction as well as a markedly restricted repertoire of activity and interest as well as repetitive patterns of behavior.
autosomal dominant polycystic kidney disease (1 paper, 2022). Autosomal dominant form of polycystic kidney disease. "Most recently, Raby found that PKP4 is presented in the urine exosome in patients with Autosomal Dominant Polycystic Kidney Disease (ADPKD) as poor treatment responder biomarker." (PMID 35351150, 2022).
bladder cancer (1 paper, 2023). "It is possible that low levels of PKP4 facilitate increased the motility of bladder cancer cells, conferring an aggressive, metastatic disease." (PMID 36672328, 2023). "As yet, the role of PKP4 in bladder cancer is not known and other members of this family play a variable role, e.g., PKP2 is upregulated and PKP3 is downregulated in invasive bladder cancer." (PMID 36672328, 2023).
restless legs syndrome (1 paper, 2017). A condition that occurs while resting or lying in bed; it is characterized by an irresistible urgency to move the legs to obtain relief from a strange and uncomfortable sensation in the legs. "The BI-ENRICH algorithm showed that most of the top pathways identified for restless legs syndrome were related to neurodevelopment, including neurogenesis (genes MDGA1, MYT1, NTNG1, and SEMA6D), cell-junction organisation (PKP4 and SMAD3), and axon guidance (NTNG1 and SEMA6D)." (PMID 29029846, 2017).
Stroke (1 paper, 2023). Sudden impairment of blood flow to a part of the brain due to occlusion or rupture of an artery to the brain. "Investigations of PKP4, DLG1, DLG2, PTPRS and OBSL1 found insufficient evidence to provide a direct link between these genes and neurodegenerative or stroke events." (PMID 37422595, 2023).
cancer (6 papers, 2012 to 2025). A tumor composed of atypical neoplastic, often pleomorphic cells that invade other tissues. "In carcinomas, the genes related to cell adhesion molecules are MACROD1, CELSR1, and PKP4, with a high-impact mutation detected in PKP4." (PMID 40446009, 2025). "At the pan-cancer level, most signaling pathways, particularly PKP4, PKP2, JUP, and CTNND2, showed high levels of activation in the Hormone AR signaling pathway, but consistent inhibition of apoptosis, cell cycle, and DNA damage responses." (PMID 37924160, 2023). "Based on our findings that PKP4 is an important regulator of an ARHGEF2-RhoA-ROCK/MLCK signaling axis, it is tempting to speculate that this function of PKP4 may contribute to cancer." (PMID 38970683, 2024). "The lack of these cancer stem cell markers, specifically SEMA5A (semaphorin 5A), KITL (KIT ligand, stem cell factor), CAV2 (caveolin 2), EPS8 (epidermal growth factor receptor pathway substrate 8) and PKP4 (plakophilin 4), was associated with acquired resistance to radiation in this study." (PMID 33767581, 2021).
tumor (6 papers, 2012 to 2022). "The analysis of the transposon integration sites identified several candidate genes, of which Man1a1, Pkp4, Rab10, Rasa1, Trps1, Vps26a, Xpnpep3 and Znf326 accelerated tumor growth, whereas the silencing of R3hcc1l reduced tumor growth." (PMID 36497409, 2022). "FLCN has been shown to bind FNIP1, FNIP2, the Rag GTPases A and C/D, GABARAP and plakophilin-4 (refs 11, 12, 13, 14, 15, 16, 17, 18), but the biological significance of each of these interactions with regards to the tumour suppressor function of FLCN is under investigation." (PMID 28656962, 2017). "Gains in some of the genes involved in invasive/migratory properties (MGAT5, PKP4, ITGB6), cell cycle progression and regulation of apoptosis (RBMS1), and angiogenesis (NRXN1) may be involved in tumor development and progression." (PMID 26432421, 2015).
infection (2 papers, 2017 to 2023). The state of being infected such as from the introduction of a foreign agent such as serum, vaccine, antigenic substance or organism. "First, three FLAG-tagged armadillo repeat-containing proteins, PKP2, PKP4 (a.k.a. p0071) and β-catenin (also known as CTNNB1) were transfected into HEK293 cells, followed by infection with the PR8-Gluc." (PMID 28169297, 2017).
neurodevelopmental disorder (2 papers, 2019). A behavioral and cognitive disorder with onset during the developmental period that involves impaired or aberrant development of intellectual, motor, or social functions. "Interestingly, all four delta catenin proteins: ARVCF, catenin δ-1, catenin δ-2, and plakophilin-4 are implicated in ASD or neurodevelopmental disorders." (PMID 30814930, 2019).
PKP4 also shares sentences with these, for which no sentence is quoted: lung carcinoma (2 papers); cyst (1); emphysema (1); endometrial cancer (1); Esophageal Neoplasms (1); fragile X syndrome (1); glomerular diseases (1); heart failure (1); in velocardiofacial syndrome (1); mental disorder (1); metastatic disease (1); non-small cell lung carcinoma (1); oropharyngeal cancers (1); ovarian carcinoma (1); pancreatic adenocarcinoma (1); prostate carcinoma (1); renal cell carcinoma (1); schizophrenia (1); skin tumors (1); thymoma (1); Ventricular arrhythmia (1).